MALL (mal, T cell differentiation protein like)
Synonyms: BENE
Tractability: Antibody: its Gene Ontology location is reachable by antibodies, with high confidence; UniProt predicts a signal peptide or a membrane-spanning region.
Gene: Protein-coding gene on chromosome 2 (110,083,870 to 110,116,022, reverse strand). Ensembl gene ENSG00000144063.
Subcellular location: Membrane
Gene Ontology:
Molecular function: protein binding; structural constituent of myelin sheath
Biological process: cholesterol homeostasis; myelination
Cellular component: clathrin-coated vesicle; cytoplasmic vesicle; Golgi membrane; membrane raft; plasma membrane; membrane
Genetic constraint (gnomAD): Loss-of-function variants: 2 observed, 6.93 expected, observed/expected ratio (o/e) 0.29, 90% interval 0.12 to 0.91. That is too few expected variants to judge how well the gene tolerates losing a copy. Missense variants: 39 observed, 70.76 expected, observed/expected ratio (o/e) 0.55, 90% interval 0.43 to 0.72. Synonymous variants: 27 observed, 26.12 expected, observed/expected ratio (o/e) 1.03, 90% interval 0.76 to 1.42.
Homologues: Orthologues: chimpanzee MALL (99% identical), macaque MALL (92% identical), mouse Mall (85% identical), rat Mall (83% identical), dog MALL (82% identical), pig MALL (81% identical), rabbit MALL (81% identical), guinea pig MALL (76% identical), tropical clawed frog spef1 (42% identical), Caenorhabditis elegans F28H1.4 (25% identical), Caenorhabditis elegans F47B3.3 (19% identical). Paralogues in human: MAL (41% identical), MAL2 (37% identical), PLLP (27% identical), CMTM8 (27% identical), CMTM3 (18% identical), CMTM6 (18% identical), CMTM7 (18% identical), MARVELD1 (18% identical), PLP2 (18% identical), CMTM5 (17% identical), CMTM4 (15% identical), CMTM1 (14% identical), and 2 more.
Diseases named in the same sentence as MALL in open-access papers:
MALL is named in the same sentence as 17 diseases in open-access papers, as found by Europe PMC text mining. Sharing a sentence is not in itself a finding about the gene and the disease. The quoted sentences say what the papers report.
colorectal cancer (2 papers, 2016 to 2018). A primary or metastatic malignant neoplasm that affects the colon or rectum. "MALL is down-regulated in colorectal cancers, with this low expression predicting tumor recurrence, metastasis and poor outcome." (PMID 30131849, 2018). "Suppression of MALL expression in tumor tissues negatively affects colorectal cancer patient survival." (PMID 26992238, 2016). "MALL may play a role in colorectal cancer progression as suppression of its expression in tumor tissues negatively impacts colorectal cancer patient survival." (PMID 26992238, 2016). "Therefore, MALL may play a role in colorectal cancer progression and may represent a novel therapeutic related and/or diagnostic marker." (PMID 26992238, 2016). "MALL, PHLDB2 and other genes responsive to APC are consistent with the emerging role of canonical WNT signaling targets in colorectal cancer invasion and progression, in addition to the better-characterized role of the pathway in colorectal tumor initiation." (PMID 30131849, 2018). "Finally, overexpression of MALL suppressed HCT116 and SW480 cell proliferation and inhibited HCT116 migration, suggesting that reduced MALL expression contributes to colorectal cancer progression." (PMID 26992238, 2016).
lung carcinoma (2 papers, 2010 to 2023). "Other stronger correlations were that of MAL (LUAD) and MYADM (LUSC) in lung cancer, which was the second most highly ranked in the 2020 ranking, with 12.5% of the new cancer cases, and that of MAL2 and MALL in PAAD, which was ranked twelfth, with 2.7% of the new cases." (PMID 37345137, 2023). "The scrutiny of the two sources of information, datasets and published studies, reveals potential prognostic applications of MAL-family members as cancer biomarkers—for instance, MAL2 in breast cancer, MAL2 and MALL in pancreatic cancer, and MAL and MYADM in lung cancer—and other biomedical uses." (PMID 37345137, 2023).
pancreatic cancer (2 papers, 2022 to 2023). "Since MALL is highly upregulated in pancreatic cancer, it could produce aneuploidy, which is a hallmark of cancer." (PMID 37345137, 2023). "In the case of pancreatic cancer, MALL RNA is expressed in large excess compared with normal tissue, and its overexpression correlates with an unfavorable patient outcome." (PMID 35399121, 2022). "The anti-MALL mAb 2G8 described in this study constitutes a unique tool for investigating the acquisition of the two alternative structures of MALL further, for analyzing its role in cancer, and for establishing pancreatic cancer prognosis." (PMID 35399121, 2022). "Excess MALL promotes aberrant nuclei and, consistent with the unfavorable prognosis of MALL overexpression in pancreatic cancer, might contribute to cell malignancy." (PMID 35399121, 2022). "Therefore, the alteration produced by an excess of MALL could contribute to pancreatic cancer by producing aberrant nuclei." (PMID 35399121, 2022). "Bioinformatic analysis revealed that, although it was not statistically significant, there is a trend between high levels of MALL expression and aneuploidy in pancreatic cancer, suggesting that MALL overexpression could contribute to cell malignancy by promoting nuclear aberrations." (PMID 35399121, 2022).
prostate carcinoma (2 papers, 2008 to 2009). A carcinoma that arises from epithelial cells of the prostate gland. "Although loss or decreased MALL expression has not been evaluated in human prostate cancer, the expression of this protein in normal prostate epithelium and its ability to suppress invasion and motility render it a biologically plausible metastasis suppressor gene for prostate cancer." (PMID 19781100, 2009). "Compared to several other learning algorithms, MDR gives the greatest AUC (area under the ROC curve) for the classifications of prostate cancer, acute lymphoblastic leukemia (ALL) and four ALL subtypes: BCR-ABL, E2A-PBX1, MALL and TALL." (PMID 18831787, 2008).
colon cancer (1 paper, 2016). "To determine whether MALL expression is associated with colon cancer progression and patient survival, we analyzed its expression in colon and rectal cancer tissues and its association with patient clinicopathological characteristics." (PMID 26992238, 2016). "The aim of the present study was to determine whether MALL expression is associated with colon cancer progression and patient survival." (PMID 26992238, 2016). "MALL mRNA expression was reduced in the tumor tissues of 70% of the colon cancer patients and 75% of the rectal cancer patients as compared to their normal tissues." (PMID 26992238, 2016). "We previously found greatly reduced expression of MALL in colon cancer tissues using a SAGE database." (PMID 26992238, 2016). "In the present study, MALL mRNA expression was confirmed by real-time PCR analysis of normal and tumor tissues isolated from 40 patients with colon cancer and 40 patients with rectal cancer with actin as the internal reference." (PMID 26992238, 2016). "In patients with colon cancer, the global expression (ΔCT) of MALL was 13.16 ± 1.37 in tumor tissue and 11.44 ± 0.90 in normal tissue (P < 0.001); the relative expression (2ΔΔCt) was 0.62 ± 1.08 (range 0.03 - 6.08)." (PMID 26992238, 2016). "Immunohistochemical analysis of 203 normal and colon cancer pairs revealed that the distribution of MALL expression was significantly different between normal and tumor tissues (P < 0.001)." (PMID 26992238, 2016). "MALL protein was also significantly reduced in the tumor tissues of colon cancer patients (P < 0.001)." (PMID 26992238, 2016). "Because MAPK/ERK signaling pathways are known to drive cell proliferation, survival and metastasis, we analyzed the levels of ERK phosphorylation in MALL-overexpressing SW480 and HCT116 cells to further elucidate the role of MALL in colon cancer cell proliferation and invasion." (PMID 26992238, 2016). "MALL LOH was analyzed by real-time PCR analysis of normal and tumor tissues from 40 patients with colon cancer and 40 patients with rectal cancer with three different primer sets as well as PMP as the internal reference." (PMID 26992238, 2016). "Of the 203 colon cancer patients whose tissues were analyzed by immunohistochemistry, 58 subjects (20 males and 38 females) had MALL-negative tumors." (PMID 26992238, 2016).
developmental delay (1 paper, 2021). "A copy number loss encompassing a similar interval (including MALL, NPHP1, LIMS3, RGPD6, and BUB1) has been reported in ClinVar as a variant of uncertain significance with the phenotype of developmental delay and facial dysmorphisms (SCV000709783.2)." (PMID 33597717, 2021).
Juvenile nephronophthisis (1 paper, 2023). "The MALL gene, also called BENE, was independently identified in searches for non-Vκ transcripts from the immunoglobulin κ locus and for candidate genes for familial juvenile nephronophthisis." (PMID 37345137, 2023).
kidney cancer (1 paper, 2022). Primary or metastatic malignant neoplasm involving the kidney. "We observed that the mRNA expression level of ETV4 was significantly increased and the expression levels of SH2B3, FATE1, GRK5, MALL, HRH2, SEMA3G and SLC10A6 were decreased prominently in kidney cancer cells when compared with HK2 cell line." (PMID 36059531, 2022). "Furthermore, we detected the mRNA and protein expression levels of 8 epi-PCGs (ETV4, SH2B3, FATE1, GRK5, MALL, HRH2, SEMA3G and SLC10A6) in 4 human kidney cancer cell lines (786-O, A498, Caki-1 and ACHN) and the normal human renal tubular epithelial cell line HK2." (PMID 36059531, 2022).
rectal cancer (1 paper, 2016). A primary or metastatic malignant neoplasm that affects the rectum. "Similarly, in patients with rectal cancer, the global expression of MALL was 15.54 ± 2.22 in tumor tissue and 13.15 ± 2.04 in normal tissue (P < 0.001), and the relative expression was 2.85 ± 10.80 (range 0.002 - 57.48)." (PMID 26992238, 2016). "In the present study, the reduced MALL expression was confirmed in colon and rectal cancer and normal tissues using real-time PCR analysis and immunohistochemistry, and the correlation of MALL expression levels with patient survival and clinicopathological characteristics was also evaluated." (PMID 26992238, 2016). "However, further detailed analyses of the mechanisms of MALL downregulation are necessary to examine whether LOH and methylation are cooperative events or different mechanisms as well as to determine if these events are found in the majority of colon and rectal cancers or only specific subsets." (PMID 26992238, 2016).
rectal tumors (1 paper, 2016). "In the present study, MALL expression was greatly reduced in colon and rectal tumor tissues as compared to normal tissues, and ectopic expression inhibited HCT116 and SW480 cell proliferation and HCT116 migration, suggesting that MALL may have a similar tumor suppressor function in colorectal cells." (PMID 26992238, 2016).
cancer (9 papers, 2009 to 2026). A tumor composed of atypical neoplastic, often pleomorphic cells that invade other tissues. "Disruption of the axis through SPHK1 knockdown in CAFs, genetic perturbation of MALL or SDC4 in cancer cells, or adeno-associated virus-mediated SPHK1 or SDC4 knockdown in KPC (KrasLSL-G12D/+; Trp53LSL-R172H/+; Pdx1-Cre) mice significantly reduces PNI and tumor burden." (PMID 42017444, 2026). "Given the role of polarity loss in cancer cell metastasis, further studies will assess whether MALL influences apical transport in a similar fashion as MAL." (PMID 26992238, 2016). "Loss of or decreased MALL expression, sometimes as the result of DNA methylation of the promoter region, has been found in a variety of benign and malignant epithelial tumors compared to their normal epithelial counterparts, consistent with a role for this protein in tumor suppression." (PMID 19781100, 2009). "MAL proteolipid family (MALs), including T‐cell differentiation protein (MAL), T‐cell differentiation protein 2 (MAL2), and T‐cell differentiation protein like (MALL), were involved in the progression and prognosis of many different cancers." (PMID 40625454, 2024). "MALL is found to be involved in multiple cellular processes in cancer cells and is highly elevated in multiple aggressive cancer types." (PMID 37033945, 2023). "MAL (LUAD, THYM, and UCEC), MAL2 (BRCA, PAAD, and UCEC), and PLLP (KICH, KIRC, and UCEC) present strong correlations (p ≤ 0.001) in three types of cancer, and MALL (KIRC and PAAD), CMTM8 (KIRC and KIRP), and MYADM (LUSC and THYM) do so in two cancer types." (PMID 37345137, 2023). "MALL is a member of the MyD88 adapter-like (Mal) family of proteins that have role in various cancers." (PMID 26992238, 2016). "In a previously established SAGE database, we observed that the MALL gene signal was significantly reduced in carcinoma tissue as compared to normal tissue (P < 0.001)." (PMID 26992238, 2016). "This points to MALL as being a possible target for cancer treatment." (PMID 35399121, 2022). "In addition, the expression of the T-cell differentiation protein-like, MALL (NM_005434.4), was greatly reduced in carcinoma tissue as compared to normal tissue." (PMID 26992238, 2016). "Therefore, excess of MALL in some cancers could contribute to malignancy by inducing chromosome instability." (PMID 37345137, 2023). "During mitosis, MALL accumulated in solid-like condensates around the spindle but, when in excess, the condensates mis-localized, altered the distribution of the nuclear proteins emerin LAP2β and BAF, and caused nuclear aberrations, which are a hallmark of cancer cells." (PMID 35399121, 2022). "MALL expression was upregulated in PAAD, but reduced in 70–75% of COAD-READ cancers compared with normal tissues." (PMID 37345137, 2023). "Myelin and lymphocyte protein (MAL), MAL2, MAL like protein (MALL, formerly BENE) are involved in several human cancers 23,118,119, either promoting or suppressing tumor growth and metastasis 120-122." (PMID 37928877, 2023). "Similar effects were observed for exogenous MAL2 in prostate, pancreatic, lung, and liver cancer cells; for exogenous MALL in colorectal cancer cells; and for CMTM8 in liver, pancreatic, and urothelial cancer cells." (PMID 37345137, 2023). "Reports about promoter methylation of MAL-family genes in cancer are available only for MAL, MAL2, and MALL." (PMID 37345137, 2023).
tumor (9 papers, 2009 to 2026). "MALL, FHL2, PHLDA, NR4A3 and CTGF are known oncogenic factors and its gene expression is negatively associated with tumor-free survival and/or proliferation." (PMID 26187749, 2015). "Increased LOH and methylation of MALL was observed in tumor tissues as compared to normal tissues." (PMID 26992238, 2016). "In the present study, increased MALL methylation was noted in tumor tissues, and MALL-negative tumors were associated with reduced patient survival." (PMID 26992238, 2016). "In addition to MALL tumor expression, OS and DFS were significantly associated with N category, M category, vessin invasion status, tumor differentiation, and AJCC stage (all P ≤ 0.009)." (PMID 26992238, 2016). "The methylation status of MALL was next assessed to determine if this could account for the reduced MALL expression in tumor tissues." (PMID 26992238, 2016). "This is especially evident in the cases of MALL, PLLP, and MYADM, whose function in normal and tumor cells needs further investigation using established cell model systems, and that in the case of MYADML2, which is yet to be examined." (PMID 37345137, 2023). "MAL-family proteins overexpressed in tumor cells —for example, MAL2 in BRCA, PAAD, and UCEC, and MALL in PAAD—could serve as putative target antigens for CAR-T cell therapy." (PMID 37345137, 2023). "A significantly greater percentage of tumor tissues were negative for MALL expression as compared to normal tissue (28.6% vs. 7.9%, P < 0.001)." (PMID 26992238, 2016). "MALL mRNA and protein expression was reduced in the tumor tissues analyzed, which may be due to LOH and/or methylation of the MALL gene." (PMID 26992238, 2016).
MALL also shares sentences with these, for which no sentence is quoted: acute lymphoblastic leukemia (1 paper); breast carcinoma (1); cervical tumors (1); colorectal tumor (1); gynecologic cancers (1).